CD4 (CD4 molecule)
Diseases named in the same sentence as CD4 in open-access papers (continued):
Sharing a sentence is not in itself a finding about the gene and the disease.
tumor (continued). "Moreover, CCL5 can induce the immunosuppressive polarization of macrophages, initiate the Th2 differentiation of CD4+ T cells and recruit Tregs to form tumor suppressive environments." (PMID 35327361, 2022). "Indeed, tumor-antigen specific CD4+ T cells with Th1 polarization can indirectly promote tumor rejection by cytokine production to support survival and stimulate CTL and Natural Killer (NK) cell functions into the tumor." (PMID 35008422, 2022). "Interestingly, treatment with the combo gel increased the ratio between CD8+ and CD4+ T cells, indicating that more cytotoxic T cells infiltrated into the tumor." (PMID 35780226, 2022). "Furthermore, P-selectin promotes tumor metastasis by functional inhibition of CD4+ and CD8+ T cells via infiltration of regulatory T cells and aggregation of other cells." (PMID 35936717, 2022). "The tumor tissue of patients with VISTA expression on CD4+ T cells had a lower level of cytokines." (PMID 35122478, 2022). "Indeed, after the CD4/8pos T and CD15pos cells co‐removal, the tumor cell death was significantly reduced to a level even lower than the control conditions." (PMID 35611994, 2022). "The resulting decreases in intratumoral granulocytic‐myeloid‐derived suppressor cells and regulatory T cells could facilitate the observed increase in tumor‐infiltrating CD4+ T cells." (PMID 35243806, 2022). "Mouse spleen immune cell analysis revealed that B. microti-infected tumor-bearing mice could increase the number of macrophages and CD4+ T cells, as well as the proportion of CD4+ T cells and M1 macrophages in the tumor." (PMID 35814662, 2022). "Therefore, any TCR transduced T cell culture used for patient treatment can contain both MHC class I restricted, tumor reactive CD4+ and CD8+ T cells if engineered with a high affinity TCR." (PMID 35335089, 2022). "Characterization of the Tumor Immune Microenvironment (TIME) involved the immunohistochemical analysis of PD-L1, and number and distribution of CD3+, CD4+, CD8+ Tumor Infiltrating Lymphocytes (TILs) and CD163+ Tumor Associated Macrophages (TAMs), focusing on immune-vascular localization." (PMID 35805021, 2022). "It has been found that ICB could regulate the abundance and function of CD4+ T cell which reduced the number of Tregs and synergized the anti-tumor effects of CD8+ T cells." (PMID 35495133, 2022). "Samples of pancreatic tissue and blood aliquots examined by flow cytometry for signs of an adaptive anti-tumor immune response revealed the percentage of CD4+ and CD8+ among CD3+ lymphocytes to be unchanged on day 14, i.e., following the conclusion of oncolytic construct administration." (PMID 35454928, 2022). "CD4+ T cells are essential to the anti-tumor immune response." (PMID 36618354, 2022). "Further interrogation of the FACS data showed that the tumour-infiltrating NK cells associated with 5-FU treatment did not express high levels of Kv1.3; hence, [18F]AlF-NOTA-KCNA3P was instead likely measuring increases in tumour-infiltrating Kv1.3-expressing CD4+ TEM cells." (PMID 36289605, 2022). "Our data also suggest that the hepatic CD8+ and CD4+ Te phenotypes might initially have anti-tumor function but could promote tumor growth when they remain chronically elevated throughout a WD." (PMID 35235789, 2022). "Therefore, 60% of CD4+ T cells in spleens of untreated non-tumor–bearing mice expressed FOXP3 as a marker for Tregs (p < 0.0001)." (PMID 35782876, 2022). "The tumor samples have been stained with CD4, CD8, CD68, and MMP9 immune stain markers." (PMID 35083113, 2022). "Targeting tumor-specific antigens to the autophagy pathway might be a promising approach to CD4+ T cell-based cancer immunotherapy." (PMID 36139357, 2022). "Beside killing target cells NK cells may exert regulatory functions, e.g., facilitating the differentiation of CD4 T cells into Th1 cells, to enhance anti-tumor responses." (PMID 35237269, 2022).
tumor (continued). "In addition to MDSCs, Tregs cells also represent a target because tumor infiltrating FoxP3+ CD25+ CD4+ Tregs cells are highly proliferative and suppressive." (PMID 36159809, 2022). "Tumor-infiltrating immune cells can affect the response to immunotherapy, and expression levels of immune checkpoint genes can be upregulated by tumor-infiltrating CD4+ T cells." (PMID 36389694, 2022). "C-Myc induces tumor cells to evade immune detection and cytotoxic T cell responses by decreasing antigen presentation of HLA-DM and CD4+ T cells and down-regulating the expression of adhesion molecules (LFA-1, CD54, CD58) and costimulatory molecules (i.e., CD40)." (PMID 35359945, 2022). "Previous studies have found that CD4+ T cells have a positive impact on tumor immunity." (PMID 36186450, 2022). "They observed that the system co-delivered CpG oligonucleotide and MPLA together with Trp2 peptide, orchestrating robust host immune responses, including CD8+ T cells, CD4+ T cells, and macrophages, extending median survival significantly in tumor-bearing mice." (PMID 35745800, 2022). "In some tumours, B cells represent a considerable portion of infiltrating cells and contribute to tumour rejection by presenting antigens, by secreting tumour-targeting antibodies that induce tumour cell apoptosis, and by secreting cytokines that prime effector CD4+ and cytotoxic CD8+T cells." (PMID 35350071, 2022). "Accordingly, it was suggested that the rescue of these intrahepatic CD4+ T cells from apoptosis might prevent tumor initiation and aid in immunotherapy for NAFLD-promoted HCC." (PMID 36428596, 2022). "Furthermore, CD4+ T cell depletion similarly upregulated PD-1 expression in the remaining CD8+ T cells in the tumor in both CD- and HFD-fed mice." (PMID 36611881, 2022). "FOXP3 expression decreased in tumor-bearing mice demonstrating a switch to activate CD4+ T cells." (PMID 35782876, 2022). "In addition, the study demonstrated that tumor cell-derived exosomes can deliver miR-214 to CD4 T cells in human cancers, which ultimately reduced phosphatase and tensin homolog production and accelerated Treg cell expansion and tumor growth." (PMID 35711455, 2022). "CD161 is expressed by several lymphocyte populations, but its role and regulation on tumor-specific CD4+ T cells is unknown." (PMID 35039463, 2022). "Moreover, CD4+ T cells also help to maintain CD8+ memory T cells in order to generate an effective secondary anti-tumor immune response." (PMID 36005179, 2022). "Thus, more research will be needed to understand GzA expression of CD4+ cyTreg in tumor models, determine the exact role of GzA and GzB for in vivo suppression, and evaluate CD4+ cyTreg anti-tumor potential in vivo." (PMID 35493508, 2022). "TICs are functionally divided into two categories: 1) tumor cell growth inhibition including CD8+ T, Th1 CD4+ T, Th9 CD4+ T, plasma, memory B, NK cells, and DCs; 2) tumor cell growth or immune escape stimulation including Treg, Breg, macrophage M2, and myeloid-derived suppressor cells, (MDSCs)." (PMID 36468013, 2022). "The expression of VISTA on CD4+ T cells could regulate tumor immunity and serve as a prognostic indicator for survival outcomes." (PMID 35122478, 2022). "Our data also revealed an association of low percentages of CD3+CD4+HLA-DR+ T cells and CD3+CD8+HLA-DR+ T cells with CR in HL, which implied that HLA-DR+ T-cell activation may help tumor cells to escape immune surveillance." (PMID 36035394, 2022). "Indeed, CD4-depletion reduced induction of both virus- and tumor-reactive CD8+ T cells upon NDV-Flt3L treatment." (PMID 36418317, 2022). "Thus, the help of CD4+ T cells is not as critical for acute stimulation of a memory response, as corroborated by individual tumour growth in which the CD4+ T cell depleted animals had significant tumour regression initially." (PMID 35808806, 2022).
tumor (continued). "Interestingly, both mice treated with either ENI or tumor only SBRT had an increase in CD4 T cells expressing IFNg compared to anti-CD25 only treated mice." (PMID 36385142, 2022). "Another different issue is whether tumor infiltration with CD4 T cells plays a role in anti-tumor immunity." (PMID 36362027, 2022). "We showed that PD-1 and CD39 co-expression in conventional memory CD4 T cells in blood could be used as a surrogate marker to unveil the existence of an active anti-tumor adaptive immune response." (PMID 35954341, 2022). "In addition, elevated numbers of infiltrating Tregs expressing ICs inhibit the activation of CD8+ and CD4+ T cells within the tumor." (PMID 36146549, 2022). "In addition, we found that the frequencies of tumor-infiltrating IFN-γ + CD4 + T cells and IFN-γ + CD8 + T cells decreased significantly after treatment with CDDP, but when CDDP was combined with I/R, the frequencies of these cells increased significantly." (PMID 36057637, 2022). "The estimated CD4+ T-cell density at the IM was significantly associated with low tumor stage (p < 0.0001), negative nodal stage (p = 0.024) and linked to prolonged overall and progression free survival (≤0.012)." (PMID 36077784, 2022). "Tumor immune infiltration analysis showed that a high level of CXCL13 and corresponding high risk of LUAD were positively correlated with the activation of B cells, CD4+ T cells, CD8+ T cells, and dendritic cells." (PMID 35844446, 2022). "We hypothesized that, in similar way, effector CD4 T were able to modify the function of TAMs to induce tumor rejection." (PMID 35903540, 2022). "In the same year, the same group of researchers co-expressed B7-H6–specific CAR and the transcription factor T-bet (T-box expressed in T cells); CD4+ T cells were found to enhance the toxicity to B7-H6+ tumor cells and improve survival in a RMA/B7-H6 lymphoma mouse model." (PMID 36466873, 2022). "In tumor tissues, we also found that the CD4-CIK group had a lower number of CD8+ T cells, a higher percentage of PD-1+Tim-3+CD8+ T cells (generally considered to be terminally exhausted T cells), and a poorer cytotoxic function in tumor tissues than the CIK group." (PMID 35523765, 2022). "Additionally, CD4+ Th-17 cells can induce tumor growth after being activated by TGF-β, IL-6, or IL-23." (PMID 36551522, 2022). "Similar results were obtained against tumor-specific CD4 T-cell response." (PMID 35935946, 2022). "Although studies have largely focus on CD8 + TRM within HNSC, interestingly, the tumor microenvironment itself may play a role in inducing and sustaining both CD4 + and CD8 + TRM populations within the tumor." (PMID 34743182, 2022). "Data from 12 NSCLC patients suggested that multiple non-mutated neoantigens released from cisplatin-induced apoptotic tumor cells elicited CD8+ or CD4+ Teff cell responses, which could notably be promoted by anti-PD-1 therapy, correlating with OS." (PMID 36189283, 2022). "A later study by the same group found that rejection of different tumors that are primarily controlled by CD8+ T cells was correlated with inhibition of tumor-induced angiogenesis likely via an IFNγ-dependent mechanism, suggesting a shared mechanism for tumor rejection by both CD4+ and CD8+ T cells." (PMID 36159781, 2022). "Flow cytometry analysis showed that priming of the tumor microenvironment with tranilast enhanced the antitumor responses of immunotherapy as indicated by the accumulation of CD4+ and CD8+ T cells and the concomitant increase in the cytotoxic to regulatory T cell ratio." (PMID 36418896, 2022). "Treatment with chemotherapy and anti-PD-1 may have resulted in the influx of (neoantigen-specific) CD4+ T cells to the tumor, suggesting an active, although clinically ineffective, response." (PMID 35361728, 2022). "Moreover, evidence has been provided on the possibility that GBM, through DNA methylation of key genes, dictates the fate of tumor infiltrating CD4+ T cells." (PMID 35805021, 2022).
tumor (continued). "In addition to NK cells, platelet-derived TGF-β converts CD4+ T cells into inducible regulatory T cells and exerts anti-tumor immunity by attenuating tumor-infiltrating lymphocytes." (PMID 35936717, 2022). "The correlation between abundance ratios of the four immune cells and clinical characteristics reveals that CD8 + T cells, Plasma cells, and resting CD4 + T memory cells decreased with the increase of stage T, clinical stage, and tumor grade, while M2 Macrophages is the opposite." (PMID 35397536, 2022). "As a major component of the TME, CD4+ T cells may attack tumor cells directly through cytolytic responses or indirectly through regulating other lymphocytes, such as strengthening B cell and cytotoxic T cells (CTLs) responses." (PMID 36173625, 2022). "Moreover, a significant decrease in CD4+ Tregs was observed already 11 days after the treatment in nsECT4-treated mice compared to healthy and untreated tumour-bearing mice." (PMID 36551739, 2022). "To determine the role of these host cells played in the control of metastasis following activated tumor-specific CD4+T cell transfer, we used Cd4–/– mice, Cd8–/– mice as recipient mice and found that CD4+ T-cell adoptive transfer also significantly reduced metastatic foci in the lung of these mice." (PMID 35784297, 2022). "Salmonella can enhance the immune response to tumor cells by increasing the tumor-infiltration of different innate and adaptive immune cells such as CD4+ helper T cells, CD8+ cytotoxic T cells, B cells, macrophages, neutrophils and natural killer (NK) cells 21-23." (PMID 36118522, 2022). "Splenic CD8+ T cells harvested from either no TX group or pIL-12 GET treatment group, these cells were capable of producing the key effector cytokines IFN-γ and granzyme B, the splenic CD8+ T cells from tumor-bearing mice induced higher IFN-γ production from day 8 compared to CD4+ T cells." (PMID 36365247, 2022). "Moreover, we found that the expression of these gene sets has a closely association with tumor immune cell infiltration (Cor = 0.78), including Tfh, Th1, CD8 T cell, exhausted cell, NK cell, macrophage, DC, and CD4 T cell." (PMID 35368338, 2022). "Second, abnormal cellular immune function in PTB patients, such as the imbalance of Thl/Th2 proportion in helper T cells or the decrease of CD4+ T cells, will lead to the weakening of anti-tumour immune function and the increase of cancer cell escape, thus promoting tumour formation." (PMID 35105410, 2022). "Additionally, sufficient studies have demonstrated that CD4 + T cell infiltration is related to the efficacy of tumor treatment with immunotherapy and that more abundant CD4 + T cell infiltration usually means that a tumor is “hot” to immunotherapy." (PMID 35739504, 2022). "Therefore, the low level of CD4+TIL-Ts in CD8-predominant AITL also indicated that anti-tumor immunity was downregulated." (PMID 36325319, 2022). "In summary, the role of DOCK8 on cytoskeleton reconstruction, CD4+ T cell differentiation, immune synaptic formation, tumor immune infiltration and tumor immune surveillance might be the main mechanisms for the function of DOCK8 on tumorigenesis." (PMID 36386145, 2022). "PAP-AuNPs could activate tumor-bearing mice’s immune system by increasing CD4+/CD8+ ratio in peripheral blood, spleen index and thymus index." (PMID 35363110, 2022). "Similarly, our analyses of T cell reactivity against tumor-specific neoantigens have shown that DP CD4+ and CD8+ T cells recognized different peptides." (PMID 35439168, 2022). "As IFN-γ is an important anti-tumor cytokine and ALKBH5 has a positive effect on the expression of IFN-γ in autoimmunity, ALKBH5 may have the potential to positively regulate the anti-tumor effect of CD4+ T cells." (PMID 35296338, 2022). "While a CD4 + subset of Treg cells may induce immune-suppressive functions in the setting of tumor or pathogen responses, Treg cells may also provide a protective role in the setting of pulmonary damage during viral infection." (PMID 35354833, 2022).
tumor (continued). "To further understand the relationship between B7 family expression and infiltrating immune cell type, we analyzed six tumor-infiltrating immune cell types (B cells, CD4 T cells, CD8 T cells, neutrophils, macrophages, and dendritic cells) in the immune microenvironment." (PMID 36311731, 2022). "Importantly, the number of TNFα+ and TNFαIFNγ+ CD4+ T cells significantly correlated with lower tumor growth rates, while the CD8 T cells showed a less drastic effect." (PMID 36419897, 2022). "This against distal tumor mechanism can be attributed to the comprehensive activation of the immune system by the LGG-MHS + US therapeutic strategy, which was demonstrated by immunofluorescence to substantially increase the populations of infiltrating CD8+ and CD4+ T cells in distant tumor tissues." (PMID 36550159, 2022). "Apart from the particular ability of L. monocytogenes to stimulate CD8 T‐cells via HLA‐I, translocated bacteria expressing different tumor neoantigens of 11–20 amino acids in length each are able to be presented by HLA‐II molecules on APCs and be recognized by CD4+ T‐cells." (PMID 35284089, 2022). "Next, we studied the presence of CD4+ T-cell subsets in tumor-bearing animals." (PMID 35860556, 2022). "The tumor necrosis caused by TACE increased the release of tumor-associated antigens, which has been proven to recruit DCs, increase AFP-specific CD4+T-cell response, synergize with ICIs to increase cytotoxic T lymphocytes, and decrease tumor-infiltrating Treg cells." (PMID 35530353, 2022). "Tumor-infiltrating CD4+ and CD8+ Tc displayed an effector memory phenotype." (PMID 36153593, 2022). "TGFβ blockade relieves the immunosuppression of cytotoxic CD8+ T cells and NK cells, promotes lineage switching within the CD4+ T cell population, depolarizes immunosuppressive intratumoral myeloid cells and CAFs, and inhibits angiogenesis, leading to tumor regression and long-term immunity." (PMID 36382146, 2022). "Moreover, the immunohistochemical analysis of tumor tissues similarly revealed that α5-nAChR overexpression mediated the expression of PD-L1, CD4 and GB expression." (PMID 35971127, 2022). "Conversely, we found the gene cluster A had prominently higher immune scores than other gene clusters, and it exhibited the highest activated CD8+ T cell and CD4+ T-cell infiltration, which played a central role in mediating responses to immunotherapy and controlling tumor growth." (PMID 36138406, 2022). "In addition, we present the results of studies demonstrating the prognostic and predictive value of levels of tumor-infiltrating lymphocytes (CD4 and CD8), their quantitative ratios, and their correlation with regulatory genes (PD-1, PD-L1, and FOX-P3)." (PMID 35676750, 2022). "We found that the levels of activated CD8+ T cells, CD4+ T cells, macrophages, dendritic cells, mast cells, tumor-infiltrating lymphocytes (TIL), T follicular helper cells, helper T cells, and Tregs were significantly different between the two groups (p-value < 0.05)." (PMID 36497267, 2022). "Notably, the repertoire of TILs was comparable between tumors developed in WT and Meflin-KO mice in a syngeneic tumor model, suggesting that CD4+ T-cell infiltration depends on the overall function of Meflin+ CAFs, but not specifically the function of Meflin." (PMID 35236758, 2022). "The role of CD4+ T cells in tumor eradication has drawn increasing attention in recent years." (PMID 35720407, 2022). "In fact, ACT of CD4+ T cells was ineffective in controlling tumor growth in immunocompetent hosts." (PMID 36159781, 2022). "Additionally, the population of intra-tumor CD4+CD25+Foxp3+ T cells was significantly lower in naringenin + CPT treated animals than that in controls." (PMID 35606804, 2022). "Moreover, rare intratumoral CXCR5+PD1+ICOS+ TFH and CD4+CD25+CD127− Treg cells were more frequent in the tumor than the normal liver tissue." (PMID 35724271, 2022).